DIMT1 (DIM1 rRNA methyltransferase and ribosome maturation factor)
Description:
Specifically dimethylates two adjacent adenosines in the loop of a conserved hairpin near the 3'-end of 18S rRNA in the 40S particle. Involved in the pre-rRNA processing steps leading to small-subunit rRNA production independently of its RNA-modifying catalytic activity. Part of the small subunit (SSU) processome, first precursor of the small eukaryotic ribosomal subunit. During the assembly of the SSU processome in the nucleolus, many ribosome biogenesis factors, an RNA chaperone and ribosomal proteins associate with the nascent pre-rRNA and work in concert to generate RNA folding, modifications, rearrangements and cleavage as well as targeted degradation of pre-ribosomal RNA by the RNA exosome.
Synonyms: DIMT1L; HSA9761; DIM1; HUSSY5
Tractability: Small molecule: a structure with a bound ligand is known; it has a high-quality binding pocket. PROTAC: ubiquitination databases record sites on it; its protein half-life has been measured.
Target class: Enzyme; Transferase
Gene: Protein-coding gene on chromosome 5 (62,347,284 to 62,403,943, reverse strand). Ensembl gene ENSG00000086189.
Subcellular location: Nucleus, nucleoplasm; Nucleus, nucleolus
Subcellular location (Human Protein Atlas): Nucleoli; Nucleoli rim; Cytosol; Nucleoplasm
Pathways (Reactome):
Metabolism of RNA: rRNA modification in the nucleus and cytosol
Gene Ontology:
Molecular function: 18S rRNA (adenine(1779)-N(6)/adenine(1780)-N(6))-dimethyltransferase activity; RNA binding; rRNA (adenine-N6,N6-)-dimethyltransferase activity
Biological process: positive regulation of rRNA processing; ribosomal small subunit biogenesis; rRNA methylation; rRNA modification; rRNA processing
Cellular component: nucleolus; nucleoplasm; small-subunit processome
Genetic constraint (gnomAD): Loss-of-function variants: 30 observed, 36.56 expected, observed/expected ratio (o/e) 0.82, 90% interval 0.61 to 1.11. The upper end of that interval is the gene's LOEUF score, 1.11, which puts it in group 4 of 6, group 1 being the genes least tolerant of losing a copy. Missense variants: 295 observed, 337.22 expected, observed/expected ratio (o/e) 0.87, 90% interval 0.8 to 0.96. Synonymous variants: 107 observed, 114.29 expected, observed/expected ratio (o/e) 0.94, 90% interval 0.8 to 1.1.
Homologues: Orthologues: chimpanzee DIMT1 (100% identical), pig DIMT1 (96% identical), mouse Dimt1 (96% identical), guinea pig DIMT1 (95% identical), rat Dimt1 (95% identical), dog DIMT1 (95% identical), rabbit DIMT1 (94% identical), macaque DIMT1 (91% identical), tropical clawed frog dimt1 (83% identical), zebrafish dimt1l (82% identical), Drosophila melanogaster CG11837 (67% identical). Paralogues in human: TFB1M (25% identical), TFB2M (19% identical).
Diseases named in the same sentence as DIMT1 in open-access papers:
DIMT1 is named in the same sentence as 7 diseases in open-access papers, as found by Europe PMC text mining. Sharing a sentence is not in itself a finding about the gene and the disease. The quoted sentences say what the papers report.
acute myeloid leukemia (1 paper, 2021). Acute myeloid leukemia (AML) is a group of neoplasms arising from precursor cells committed to the myeloid cell-line differentiation. "Our data suggest that downregulation of DIMT1 in acute myeloid leukemia cells leads to a decreased m26,6A level in small RNAs." (PMID 34473991, 2021). "Furthermore, we observed that DIMT1 is highly expressed in human cancers, including acute myeloid leukemia." (PMID 34473991, 2021). "Notably, DIMT1 is highly expressed in acute myeloid leukemia (AML) suggested by the data from The Cancer Genome Atlas database." (PMID 34473991, 2021).
thyroid cancer (1 paper, 2023). "Meanwhile, the colony formation assay and CCK-8 assay indicated that the overexpression of DIMT1 partially reversed the proliferation ability of thyroid cancer cells." (PMID 37564214, 2023).
viral infection (1 paper, 2025). "DIMT1 is part of the intracellular membrane-less organelle gene ontology category, which includes FMRPs, but has yet to be directly implicated in stress granule formation during viral infection." (PMID 40143373, 2025). "We are particularly interested in investigating if interactions with DIMT1, a methyltransferase, are conserved during viral infection and in biologically relevant cell lines." (PMID 40143373, 2025).
cancer (3 papers, 2020 to 2023). A tumor composed of atypical neoplastic, often pleomorphic cells that invade other tissues. "Ectopic expression of DIMT1 has been implicated in human cancer such as AML." (PMID 34473991, 2021). "As anchorage-independent growth of carcinoma cells is a key feature of their tumorigenicity, we next evaluated the function of DIMT1 on GC tumorigenesis in vivo." (PMID 37462231, 2023). "Elevated expression of DIMT1 is positively correlated with cell proliferation in cancer and the progression of multiple myeloma and colon cancer." (PMID 34473991, 2021). "DIMT1 is a methyltransferase essential for ribosome biogenesis and overexpressed in several cancers." (PMID 33055295, 2020). "Thus, we detected the expression of DIMT1 in a series of human carcinoma cell lines (MKN-28clinical TNM st, and SGC-7901 cells) and the immortalized GES-1 cells." (PMID 37462231, 2023). "Thus, we investigated if the ectopic expression of DIMT1 in cancer cells generates m26,6A in <40 nts RNAs." (PMID 34473991, 2021). "It was previously shown that elevated expression of DIMT1 is frequently seen in human cancers." (PMID 34473991, 2021). "Otherwise, DIMT1 knockdown could suppress carcinoma tumorigenesis." (PMID 37462231, 2023).
inflammation (1 paper, 2016). Aberrant reaction of the microcirculation characterized by movement of fluid and leukocytes from the blood into extravascular tissues. "DIMT1 has been linked to gastric inflammation and proliferation and was shown to be a direct miR-210 target gene." (PMID 27589845, 2016).
tumor (1 paper, 2023). "Based on the changes in the biological characteristics of the cells, we speculated that DIMT1 mutations could overactivate proliferation-related signal transduction pathways and lead to the uncontrolled growth of a tumor; meanwhile, it can adjust the expression of apoptosis-related genes." (PMID 37462231, 2023). "To directly observe the change of protein of DIMT1 in various tumor cell lines, we used the indirect immunofluorescence assay." (PMID 37462231, 2023). "We thus hypothesize that DIMT1 may be a potential tumor gene." (PMID 37462231, 2023).
DIMT1 also shares sentences with these, for which no sentence is quoted: gastric carcinoma (1 paper).